FSBP (fibrinogen silencer binding protein)
Description:
Transcriptional repressor that down-regulates the expression of the fibrinogen gamma chain. Represses transcription of GSK3B gene promoter via its interaction with APBA1.
Tractability: PROTAC: UniProt records ubiquitination sites on it; ubiquitination databases record sites on it.
Gene: Protein-coding gene on chromosome 8 (94,378,377 to 94,436,952, reverse strand). Ensembl gene ENSG00000265817.
Subcellular location: Nucleus
Subcellular location (Human Protein Atlas): Nucleoplasm
Gene Ontology:
Molecular function: identical protein binding; protein binding
Cellular component: nucleoplasm; nucleus
Genetic constraint (gnomAD): Loss-of-function variants: 18 observed, 25.4 expected, observed/expected ratio (o/e) 0.71, 90% interval 0.49 to 1.05. The upper end of that interval is the gene's LOEUF score, 1.05, which puts it in group 4 of 6, group 1 being the genes least tolerant of losing a copy. Missense variants: 305 observed, 364.7 expected, observed/expected ratio (o/e) 0.84, 90% interval 0.76 to 0.92. Synonymous variants: 110 observed, 134.05 expected, observed/expected ratio (o/e) 0.82, 90% interval 0.7 to 0.96.
Homologues: Orthologues: macaque FSBP (99% identical), guinea pig FSBP (96% identical), mouse Fsbp (88% identical), zebrafish fsbp (51% identical).
Diseases named in the same sentence as FSBP in open-access papers:
FSBP is named in the same sentence as 1 disease in open-access papers, as found by Europe PMC text mining. Sharing a sentence is not in itself a finding about the gene and the disease. The quoted sentences say what the papers report.
cancer (1 paper, 2017). A tumor composed of atypical neoplastic, often pleomorphic cells that invade other tissues. "FSBP, the mammalian homologue of Drosophila Apt, is a cancer related factor." (PMID 28963499, 2017). "The human homolog of Apt, FSBP, is a cancer-related factor that is expressed in many tissues." (PMID 28963499, 2017).